VCAM1 (vascular cell adhesion molecule 1)
Diseases named in the same sentence as VCAM1 in open-access papers (continued):
Sharing a sentence is not in itself a finding about the gene and the disease.
tumor (continued). "In addition, tumor microvessels within 4T1 tumors exhibit expression of adhesion ligands PCAM-1, VCAM-1, laminin α5 and av integrins." (PMID 23326340, 2013). "Immunoliposomes directed against multiple tumor antigens, for example, EGFR and VCAM-1 could, increase the therapeutic efficacy and, hereby, immunoliposomal therapy could become clinically significant as a novel treatment for cancer." (PMID 24175095, 2013). "Additional NF-κB target genes which contribute tumor cell migration and/or metastasis include cellular adhesion molecular, such as ICAM-1 and VCAM-1; matrix metalloproteinases, such as MMP-9; chemokine receptors, such as CXCR4, and vascular endothelial growth factor (VEGF)." (PMID 22952718, 2012). "RT can upregulate expression of adhesion molecules, such as VCAM-1, E-selectin, and ICAM-1, by vascular endothelial cells within the tumor and induce expression of T cell chemokines that promote T cell adhesion and extravasation into the tumor microenvironment." (PMID 23087904, 2012). "Previous studies showed that RT upregulated the expression of VCAM-1 on the tumor vasculature and induced the release of chemokines, such as CXCL16 from tumor cells, which may favor the trafficking of immune effector cells to the tumor tissue." (PMID 22666458, 2012). "Some researches have found that low level of vascular cell adhesion molecule-1 (VCAM-1), E-selectin, angiopoietin 2 (Ang-2) in circulation or carbonic anhydrase 9 (CA9), CD31- microvessel density (CD31-MVD) in tumor tissue can predict beter activity of bevacizumab." (PMID 21762631, 2011). "These important promoters of tumour angiogenesis include VEGF, bFGF, urokinase-type plasminogen activator and its soluble receptor, E-selectin and vascular cell adhesion molecule-1 (VCAM-1), and von Willebrand's factor (vWF)." (PMID 12838293, 2003). "N1-type neutrophils, characterized by their anti-tumor phenotype, exhibit hypersegmented nuclei and high expression levels of factors such as tumor necrosis factor-α (TNF-α), intercellular adhesion molecule-1 (ICAM-1), vascular cell adhesion molecule-1 (VCAM-1), and CCL3." (PMID 40282474, 2025). "Notably, normal tissues exhibited negative VCAM-1 staining, in contrast to tumor tissues, which exhibited medium-to-strong VCAM-1 staining." (PMID 40927361, 2025). "While primary tumor burden was not significantly altered between the 4T1-WT and Vcam1-KO groups, significant decreases in metastatic signals were observed in the lungs of 4T1-Vcam1-KO mice, as detected by biofluorescent imaging and flow cytometry." (PMID 40955669, 2025). "In addition, IL‐12‐activated NCR+ ILC3s have been shown to promote tumour rejection, not through cytotoxicity or IFNγ production, but by inducing expression of adhesion molecules like VCAM‐1 and ICAM‐1 on tumour vasculature, enhancing immune cell infiltration." (PMID 40899118, 2025). "IL-1B from osteoblasts has been shown to facilitate adhesion of circulating tumour cells to sinusoidal endothelial cells by increasing the expression of vascular cell adhesion molecules such as intercellular adhesion molecule 1 (ICAM-1), vascular cell adhesion molecule 1 (VCAM-1), and E-selectin." (PMID 38800348, 2024). "Notably, B16F10 tumor cells were different from MC38 tumor cells and expressed low/no level of VCAM1, indicating discrepant VCAM1 expression in tumor cells." (PMID 38332012, 2024). "In addition, metformin combined with anti-PD-1 therapy promotes the normalization of tumor blood vessels, increases the expression of vascular endothelial cadherin (VE-cadherin) and vascular cell adhesion molecule 1(VCAM-1), and infiltration of CD8+ T cells, and slows tumor growth." (PMID 39845945, 2024). "“T cell” neighborhoods enriched with effector T cells and mature macrophages that lacked tumor epithelium lie immediately adjacent to drug-sensitive proliferating BCC surrounded by TREM2 + VCAM1+ myeloid cells or resistant BIT tumors surrounded by lymphocyte-poor TREM1+ myeloid-driven inflammation." (PMID 39289380, 2024).
tumor (continued). "Notably, due to the impact of VCAM1 on CD8 T cells and tumor cells, blocking VCAM1-CD49d signaling could also enhance the efficacy of other immunotherapies such as CD8 T cell-based therapies." (PMID 38332012, 2024). "Next, we investigated whether blocking the VCAM1-CD49d signaling would enhance anti-tumor efficacy of iNKT cells against the VCAM1 low/no tumor cells." (PMID 38332012, 2024). "Although no liver pMF-tumor interaction was involved in this model, we reasoned that it was still a valid model for assessing Vcam1 function in iCCA development because of the high level of Vcam1 expression in PPTR lung metastases." (PMID 36828890, 2023). "We found that patients highly expressing the top 20 signature genes of IL13RA1+ E02 had shorter overall survival, further confirming their functions in tumor angiogenesis; however, signature genes of VCAM1+ E06 were not significantly correlated with clinical outcomes of patients with HGSOC." (PMID 37488416, 2023). "Tumor cells can attach to specific distant organs/tissues and form colonies through distinct adhesion molecules, including proteoglycans (e.g., CD44), mucins (e.g., MUC16), integrins (e.g., α2β1), and the members of the immunoglobulin superfamily (e.g., ICAM1, VCAM1, and L1CAM)." (PMID 38139030, 2023). "Therefore, we employed catalytic amount of or overdose suspended TIOs to co-incubate with VCAM-1 positive tumour cells, then washed twice with PBS and imaged, the results showed the TIOs could tightly bind tumour cells in both situations." (PMID 37673934, 2023). "MSCs are pluripotent stem cells with tumor-homing capacity that can transmigrate the BBB through paracellular and transcellular routes through G-protein coupled receptor and integrin very late antigen-4 and its ligand vascular cell adhesion molecule-1 (VLA-4/VCAM-1) dependent mechanisms." (PMID 37111742, 2023). "The requirement of VCAM-1 for platelet interaction with the endothelium suggests a possible mechanism in which pro-inflammatory endothelial dysregulation, facilitated by TCM, in turn recruits the anti-tumor subsets of platelets capable of maintaining and repairing endothelial integrity." (PMID 35408794, 2022). "Therefore, VCAM-1 and other adhesion molecules were believed to be significantly correlated with the invasion of HCC and could be used as a marker of tumor invasion." (PMID 36482940, 2022). "Moreover, tumor cell expression of vascular cell adhesion molecule-1 (VCAM-1), a leukocyte adhesion molecule canonically expressed on the endothelium, results in tethering of tumor cells to macrophages, and this cell-to-cell interaction promotes survival signals in metastatic cells." (PMID 33924237, 2021). "An overexpression of cellular adhesion protein, vascular cell adhesion molecule-1 (VCAM-1) in human GBM cells resulted from an activation of epidermal growth factor receptor (EGFR), was found to augment communication between macrophages and tumor cells, thus promoting tumor invasion." (PMID 34439380, 2021). "They further showed that forced overexpression of VCAM-1 in non-bone metastatic tumor cells conferred the ability to form progressive bone metastases; this was attributed to VCAM-1 interaction with its receptor integrin α4β1 on osteoclasts resulting in enhancement of osteoclast activity." (PMID 33805598, 2021). "Soluble vascular cell adhesion molecule-1 (SVCAM-1) increases tumor resistance to gemcitabine; however, combining gemcitabine with inhibition of the adhesion molecule L1CAM (CD171) reduces VEGF expression and the number of CD31-positive vessels, resulting in a stronger anti-tumor effect." (PMID 34439378, 2021). "As we did not have anti-VCAM-1 antibody monotherapy group, the effect of the antibody on tumor growth and gemcitabine resistance could not be assessed separately in this study." (PMID 33273652, 2020).
tumor (continued). "IRI-induced inflammatory cytokines, including TNF-α or IL-1, may promote the development of metastases in several types of cancer cells via the expression of adhesion molecules (e.g., e-selectin, ICAM-1, and vascular cell adhesion molecule 1 (VCAM-1)), which act as mediators for tumour growth." (PMID 32806712, 2020). "Extravasation into the tumor tissue is dependent upon interactions with adhesion molecules expressed on the immune cells themselves and the luminal surface of the tumors’ endothelial lining such as E-cadherin, intercellular adhesion molecule-1 (ICAM-1) and vascular cell adhesion molecule-1 (VCAM-1)." (PMID 33121034, 2020). "IL-1 mediated NF-kB activation in endothelial cells triggers the surface exposure of vascular cell adhesion molecule-1 (VCAM-1) and intercellular cell adhesion molecule-1 (ICAM-1), ultimately facilitating the binding of blood flowing leukocytes and possibly enhancing diapedesis of tumour cells." (PMID 33267794, 2020). "The therapeutic efficacy of the combined anti-VCAM-1 ssDNA and anti-IL4Rα RNA aptamers in tumor-bearing mice was more pronounced compared with either anti-VCAM-1 ssDNA or anti-IL4Rα RNA aptamer, as assessed by monitoring tumor growth and inhibition using noninvasive BLI and MRI." (PMID 32751068, 2020). "While both groups showed reduction of tumor volume compared to the tumors without gemcitabine, VCAM-1-overexpressing tumors showed significantly less reduction of tumor volume compared to that of control tumors (30% vs 51% reduction, respectively) after gemcitabine treatment." (PMID 33273652, 2020). "Glycans on endothelial adhesion molecules including ICAM-1, VCAM-1, and PECAM, and glycan-binding proteins (lectins) expressed on the surfaces of endothelial, immune, and cancer cells, alter the adhesive properties of endothelial cells and facilitate (or disfavor) immune and tumor cell infiltration." (PMID 31195728, 2019). "CXCL 12, integrins, osteopontin, vascular cell adhesion molecule-1 (VCAM-1), transforming growth factor beta (TGF-beta) and the receptor activator of nuclear factor kappa-b ligand (RANKL) are have been reported to influence the metastatic niche specificity for tumor type." (PMID 30180883, 2018). "No obvious tracer uptake could be seen in the imaging of A375m, MDA-MB-231, and 786-O tumor models, which are consistent with the lack of VCAM-1 expression in these tumor tissues and also confirmed by immunofluorescence staining of the tissues." (PMID 29853809, 2018). "Furthermore, vascular cell adhesion molecule-1 (VCAM-1), an angiogenic factor and MT1-MMP, an enzyme, both expressed on the tumor endothelial cells in several tumor types are also considered as potential broad-spectrum targets for ligand-mediated nano-chemotherapeutics." (PMID 30429787, 2018). "Similarly, in tumor microenvironments or tumor vasculature or endothelium of tumor neovasculature, overexpressed receptors include; VEGF receptor, ανβ3 integrin receptor, vascular cell adhesion molecule-1 (VCAM-1) glycoprotein and MMPs." (PMID 30429787, 2018). "Additionally, integrin α4β1 and its ligand, vascular cell adhesion molecule-1 (VCAM-1), have been demonstrated to be important in vessel formation in both tumor and non-tumor settings." (PMID 29026524, 2017). "The blocking of neither ICAM-1 nor VCAM-1 had any effect on the PT-induced tumor cell adhesion." (PMID 29100413, 2017). "The tumor tissues were implanted into nude mice and subjected to pathological examination, immunohistochemical staining, and real-time PCR for cytokeratin 8/18 (CK8/18), E-cadherin, vascular cell adhesion molecule-1 (VCAM-1) and intercellular adhesion molecule-1 (ICAM-1)." (PMID 26847082, 2016). "Adhesion molecules including ICAM-1, VCAM-1, and E-selectin may be absent or expressed at low levels on tumor vasculature, despite the inflammatory microenvironment of the tumor." (PMID 28066431, 2016).
tumor (continued). "Importantly, downregulation of WISP1 in vivo also induced decrease in expression of ICAM-1, VCAM-1, VEGFC, MMP-2, MMP-9 and increase in E-cadherin, suggesting that WISP1 downregulation not only inhibited tumor growth but also suppressed tumor metastasis in vivo." (PMID 27409174, 2016). "We demonstrate that AML cell-derived R-2HG may be helpful for the establishment of a tumor-promoting bone marrow stromal niche for AML cells by producing growth-proliferating cytokine (IL-6) and enhancing cell-cell interaction (VLA-4/VCAM-1) to increase proliferation and chemoresistance." (PMID 27577048, 2016). "Therefore, reduction of VCAM-1 and EGF by combination treatment might have favorable effects in terms of inhibition of tumor cell invasion and tumor immune evasion." (PMID 25030093, 2014). "Because VCAM-1 expression is oxidative stress-inducible, in vivo administration of recombinant catalase resulted in a complete abrogation of both enhanced VCAM-1 expression by HSE cells obtained from tumor-injected mice and increased B16M cell adhesion to those HSE." (PMID 21569399, 2011). "In addition, in tumor tissues a higher expression of adhesion molecules (ICAM-1, VCAM-1, or E-selectin) in endothelial cells and a significantly higher number of infiltrated leucocytes is observed within the tumor treated with 16K hPRL compared with the untreated ones." (PMID 22087289, 2011). "Although direct co-localisation with endothelial markers was not assessed, the higher expression of ICAM-1 and VCAM-1 observed in tumour tissues relative to cultured cancer cells suggests that stromal and endothelial cells likely contribute to their expression within the tumour microenvironment." (PMID 41228228, 2025). "Similarly, after co-incubation with PLIGHT- or PαCD3&LIGHT-transfected tumor cells, the mRNA levels of chemokines and vascular adhesion molecules in vascular endothelial cells, such as CXCL-2, CXCL-8, CXCL-12, CCL-21, MADCAM-1, and VCAM-1, rose by about 2- to 5-fold." (PMID 41406950, 2025). "Tumour cells also express ICAM-1 or VCAM-1, which may not stimulate anti-tumour immunity." (PMID 40943273, 2025). "Moreover, we discovered that AMDs could not bind tumor cells if the VCAM‐1 on the tumor cells was neutralized using the corresponding antibodies, suggesting that recognition of integrins and VCAM‐1 is essential for binding." (PMID 38484186, 2024). "The realization that PS is externalized on tumor endothelial cells but not on endothelial cells in normal tissues was the result of studies on the efficacy of a coagulation-inducing vascular targeting agent (VTA) specific for vascular cell adhesion molecule 1 (VCAM1) in tumor-bearing mice." (PMID 32087708, 2020). "In addition, mainly anti-ICAM-1 and anti-VAP-1 and to a lesser extent anti-VCAM-1 mAbs inhibited HCC-derived T cell binding to tumor vascular endothelium in vitro suggesting that LFA-1/ICAM-1 and VAP-1 receptor/VAP-1 are crucial pathways mediating T cell recruitment into the tumor site in HCC." (PMID 31231358, 2019). "Interestingly, DUC18 CD8+ T cells, regardless of GW4869 treatment, entered CMS5a tumour lesions through the Sca-1+ CD31+ VCAM-1+ neovascular areas, where stromal endothelial progenitor cells (CD31+ Sca-1+) and MSCs (CD140a+ Sca-1+) were abundantly observed on the day after intravenous treatment." (PMID 29382847, 2018). "To prove whether the effect of PT on ICAM-1 or VCAM-1 expression plays a role in the PT-evoked tumor cell adhesion, we performed a cell adhesion assay, in which endothelial ICAM-1 or VCAM-1 was blocked after PT treatment by a neutralizing antibody before the (untreated) tumor cells were added." (PMID 29100413, 2017). "Furthermore, canonical vascular adhesion molecules recognized by the CTLs like ICAM-1 and VCAM-1 were not upregulated nearby the lung-residing intravascular E0771 cells as a potential means to recruit lung circulating CTLs to the vicinity of the intravascular tumor cells." (PMID 41660608, 2026).
tumor (continued). "This consistent downregulation, coupled with negative correlations to STAT3 and VCAM1 expression, especially in LSCC, supports the notion of SOX30 as a tumor suppressor." (PMID 41373817, 2025). "In PAK1KO PC cells, the expression of ICAM-1 was not changed, while VCAM-1 was increased by about 150%, suggesting that the increased ICAM-1 and VCAM-1 in PAK1KO tumour tissues were predominantly induced in non-tumour stromal cells rather than tumour cells." (PMID 41228228, 2025). "The early and marked upregulation of VCAM-1 makes this molecule a potential early biomarker for detecting metastatic activity, offering advantages over traditional imaging markers that may not clearly distinguish between tumour stages or identify early metastatic spread." (PMID 39000268, 2024). "We were intrigued by the surface marker Vcam1, which was not induced in an in vitro BMDM system, suggesting specificity to the tumor setting." (PMID 37164949, 2023). "In the past, many reports have shown that VCAM1 and STAT3 are closely related, but the specific mutual regulation mechanism is not clear at present,especially in tumor microenvironment." (PMID 37563649, 2023). "Employing neutralizing antibodies against E-selectin, ICAM-1 and VCAM-1 revealed that anti-E-selectin was able to block tumor cell binding, while anti-ICAM-1 and anti-VCAM-1 failed to significantly block tumor cell binding." (PMID 33854965, 2021). "The archazolid-induced adhesion of tumor cells was independent from the endothelial cell adhesion molecules ICAM-1, VCAM-1, E-selectin and N-cadherin, as their expression was not regulated by the compound." (PMID 30204757, 2018). "The IHC and real-time PCR results revealed that ICAM-1, VCAM-1, and CK8/18, but not E-cadherin, were predominantly expressed at surgery and in the implanted tumor of primary and first generation." (PMID 26847082, 2016). "Anti-E-selectin antibody was able to significantly block tumor cell binding, whereas neutralization of ICAM-1 and VCAM-1 did not significantly affect tumor cell binding." (PMID 26509633, 2015). "In this model we found that nonstimulated MEC and tumour cells did express E-Selectin, ICAM-1, and VCAM-1." (PMID 17088916, 2006). "Notably, knockdown of Vcam1 alone, without iNKT cell transfer plus αGC injection, impaired MC38 tumor growth, possibly due to the effect of VCAM1 on tumor cell apoptosis." (PMID 38332012, 2024). "In non-inflamed TME and highly angiogenic tumor state, bFGF/VEGF activities influence ECs toward decreased expression of endothelial adhesion molecules (EAMs), including E-selectin, ICAM1, and VCAM1, thus hindering leukocyte homing, extravasation, and infiltration into tumor tissue." (PMID 37727791, 2023). "Additionally, we also found some proteins potentially having anti-tumor properties, such as annexin A2 (ANXA2) and vascular cell adhesion molecule 1 (VCAM1), but have not been used in cancer drug development." (PMID 33287876, 2020). "Fibroblasts exposed to tumor-derived microvesicles increased expression of VCAM-1; this up-regulation could be repressed through ERK1/2 inhibition via U0126; tumor-derived microvesicles had no significant impact on fibroblast proliferation or apoptosis but did promote CAF differentiation." (PMID 32957712, 2020). "Previous studies based on parallel exome sequencing of HBsAg-seropositive HCC, observed that the virus-affected genes including VCAM1 and CDK14 only presented in PVTT but not in the primary tumor, suggesting that genes perturbed by viral integration may contribute to tumor invasive capacity." (PMID 31200735, 2019). "Therefore, aberrant expression of NF-κB induced by intrinsic or extrinsic factors may contribute to create a tumor microenvironment where a negative feedback loop inhibiting CXCR4/CXCL12 and VLA4/VCAM1 cellular communication axes allows for the maintenance of malignant cells." (PMID 27594840, 2016).